CDX2 (caudal type homeobox 2)
Description:
Transcription factor which regulates the transcription of multiple genes expressed in the intestinal epithelium (By similarity). Binds to the promoter of the intestinal sucrase-isomaltase SI and activates SI transcription (By similarity). Binds to the DNA sequence 5'-ATAAAAACTTAT-3' in the promoter region of VDR and activates VDR transcription (By similarity). Binds to and activates transcription of LPH (By similarity). Activates transcription of CLDN2 and intestinal mucin MUC2 (By similarity). Binds to the 5'-AATTTTTTACAACACCT-3' DNA sequence in the promoter region of CA1 and activates CA1 transcription (By similarity). Important in broad range of functions from early differentiation to maintenance of the intestinal epithelial lining of both the small and large intestine. Binds preferentially to methylated DNA.
Synonyms: CDX3; CDX-3; CDX2/AS
Tractability: PROTAC: UniProt records ubiquitination sites on it.
Gene: Protein-coding gene on chromosome 13 (27,960,914 to 27,975,983, reverse strand). Ensembl gene ENSG00000165556.
Subcellular location: Nucleus
Subcellular location (Human Protein Atlas): Nucleoplasm; Cytosol; Vesicles
Pathways (Reactome):
Developmental Biology: POU5F1 (OCT4), SOX2, NANOG repress genes related to differentiation
Metabolism of proteins: Synthesis, secretion, and inactivation of Glucagon-like Peptide-1 (GLP-1)
Gene Ontology:
Molecular function: DNA-binding transcription repressor activity, RNA polymerase II-specific; methyl-CpG binding; protein binding; RNA polymerase II cis-regulatory region sequence-specific DNA binding; sequence-specific double-stranded DNA binding; DNA-binding transcription factor activity; DNA-binding transcription factor activity, RNA polymerase II-specific; RNA polymerase II transcription regulatory region sequence-specific DNA binding; DNA binding; double-stranded DNA binding; sequence-specific DNA binding
Biological process: negative regulation of transcription by RNA polymerase II; animal organ morphogenesis; anterior/posterior axis specification; cell differentiation; digestive tract development; embryonic pattern specification; intestinal epithelial cell differentiation; positive regulation of transcription by RNA polymerase II; regulation of somitogenesis; regulation of transcription by RNA polymerase II; positive regulation of cell population proliferation; positive regulation of DNA-templated transcription; regulation of DNA-templated transcription
Cellular component: chromatin; nucleus; condensed nuclear chromosome; protein-containing complex; transcription repressor complex
Genetic constraint (gnomAD): Loss-of-function variants: 8 observed, 23.69 expected, observed/expected ratio (o/e) 0.34, 90% interval 0.2 to 0.61. The upper end of that interval is the gene's LOEUF score, 0.61, which puts it in group 2 of 6, group 1 being the genes least tolerant of losing a copy. Missense variants: 375 observed, 374.23 expected, observed/expected ratio (o/e) 1, 90% interval 0.92 to 1.09. Synonymous variants: 222 observed, 183.66 expected, observed/expected ratio (o/e) 1.21, 90% interval 1.08 to 1.35.
Homologues: Orthologues: chimpanzee CDX2 (99% identical), macaque CDX2 (99% identical), guinea pig CDX2 (97% identical), dog CDX2 (97% identical), pig CDX2 (96% identical), rabbit CDX2 (96% identical), rat Cdx2 (95% identical), mouse Cdx2 (93% identical), tropical clawed frog cdx2 (46% identical). Paralogues in human: CDX1 (42% identical), CDX4 (35% identical).
Diseases named in the same sentence as CDX2 in open-access papers:
CDX2 is named in the same sentence as 308 diseases in open-access papers, as found by Europe PMC text mining. Sharing a sentence is not in itself a finding about the gene and the disease. The quoted sentences say what the papers report.
colorectal cancer (169 papers, 1999 to 2025). A primary or metastatic malignant neoplasm that affects the colon or rectum. "Caudal-type homeobox 2 (CDX2) has been widely recognized as a diagnostic biomarker for colorectal cancer (CRC), and CDX2 loss is also correlated with MMR deficiency." (PMID 40001953, 2025). "Despite a low prevalence of APC mutations compared with non-CDX2-suppressed colorectal cancers, CDX2-suppressed cancers showed a higher prevalence of mutations in several other components of the WNT/APC/β-catenin pathway." (PMID 39452477, 2024). "BRAF mutations were common in CDX2-suppressed colorectal cancers (46.2%), but rare in non-CDX2-suppressed cancers (2.2%, Fisher’s exact test p < 0.0001)." (PMID 39452477, 2024). "In colorectal cancer, the alpha catalytic sub-unit of the PI3K kinase gene is frequently mutated, and PIK3CA was mutated in 30.8% of CDX2-suppressed colorectal cancers compared to 23.3% of non-CDX2-suppressed colorectal cancers (Fisher’s exact test p = 0.25)." (PMID 39452477, 2024). "All these kinases displayed mutations in more than 6% of CDX2-suppressed colorectal cancers in the TCGA cohort, and some receptor tyrosine kinases, including EGFR, ERBB3, ERBB4, RET, ROS1, and ALK, showed even higher mutation rates in these cancers." (PMID 39452477, 2024). "The genes encoding for the beta (PIK3CB) and gamma (PIK3CG) catalytic sub-units and the regulatory sub-unit 1 (PIK3R1) of PI3K were more commonly mutated in CDX2-suppressed colorectal cancers." (PMID 39452477, 2024). "Genes encoding for several components of the PI3K/AKT pathway were more commonly mutated in CDX2-suppressed colorectal cancers." (PMID 39452477, 2024). "Study showed that loss of CDX2 expression in primary tumors and lymph node metastases is specific for mismatch repair deficiency in colorectal cancer." (PMID 39328205, 2024). "CDX2 expression loss is commonly associated with mismatch repair deficiency (dMMR) in colorectal cancer (CRC)." (PMID 37325467, 2023). "Several studies have demonstrated that loss of CDX2 expression is correlated with poor outcomes in patients with colorectal cancer." (PMID 37602699, 2023). "Keratin 7-negative and keratin 20-positive phenotypes were typical for colorectal carcinomas, although the loss of CDX-2 expression was noted in some colon rhabdoid carcinomas." (PMID 36732357, 2023). "Previously, loss of CDX2 has been described as strongly associated with poor prognosis in patients with colorectal cancer." (PMID 35027037, 2022). "The Cdx transcription factors Cdx1 and Cdx2 are essential for homeostasis of the intestinal epithelium, and loss of Cdx2 has been associated with more aggressive subtypes of colorectal cancer in the human population." (PMID 33525395, 2021). "CDX2 loss or reduced expression has been associated with advanced tumor stage, including metastasis, as well as poor prognosis in colorectal cancer." (PMID 33807023, 2021). "By contrast, another study showed that for colorectal cancer, CDX2 loss was an unfavorable prognostic biomarker but only in stage IV." (PMID 33036298, 2020). "The majority of CRCs show strong nuclear expression of CDX2, although loss or reduction of CDX2 expression has been reported in 10−30% of colorectal cancer cases." (PMID 30785889, 2019). "Over the last decade, CDX2 has been linked to colorectal cancer (CRC) progression, with reduced expression of the protein associated with more advanced tumor stage, vessel invasion, and metastasis." (PMID 30257705, 2018). "Loss of caudal-type homeobox transcription factor 2 (CDX2) expression in colorectal cancers (CRCs) has recently been proposed as a promising predictive biomarker for not only prognosis but also response to chemotherapy." (PMID 29682204, 2018).
colorectal cancer (continued). "Previous studies demonstrated that VDR gene polymorphisms, which include FokI, BsmI, ApaI, TaqI, and Cdx2, are associated with ovarian, skin, breast, and colorectal cancers." (PMID 27553621, 2016). "The ROC curve for this analysis underlines the major discriminatory power of reduced Cdx2 expression for MMR-deficiency in both colorectal cancers and lymph nodes." (PMID 24130965, 2013). "To conclude, Cdx2 is significantly reduced in patients with MMR-deficient colorectal cancers, but is not limited to these tumors." (PMID 24130965, 2013). "In contrast, loss of CDX2 expression was observed in a subset of primary colorectal cancers, usually in poorly differentiated colorectal cancers." (PMID 23133598, 2012). "We hypothesize that downregulation of CDX2 promotes colorectal cancer cell migration, invasion and tumor budding predisposing patients to poor prognosis and therapy response due to increased metastasis." (PMID 40619482, 2025). "Whether other member of the EGFR family or other receptor tyrosine kinases that are also frequently mutated in CDX2-suppressed colorectal cancers are also targets of RNF43 is currently unknown." (PMID 39452477, 2024). "Moreover, reports that suggested that a loss of CDX2 is an adverse prognostic factor in colorectal cancer employed, in contrast to the current work that was based on mRNA expression, protein analysis by immunohistochemistry." (PMID 39452477, 2024). "Furthermore, enhanced CDX2 promoter methylation is associated with gene silencing in a subgroup of colorectal cancer patients with lymph node metastasis and shorter survival times." (PMID 39328205, 2024). "Interestingly, alternative ubiquitination targets of RNF43 and homologous ligase ZNRF3 at the plasma membrane include EGFR, which is deregulated by pathogenic mutations in a sub-set of CDX2-suppressed colorectal cancers." (PMID 39452477, 2024). "Similarly, the genes encoding for the proofreading polymerases POLE and POLD1 displayed significantly higher mutation rates in CDX2-suppressed colorectal cancers." (PMID 39452477, 2024). "However, CDX2-suppressed colorectal cancers had a higher prevalence of mutations in alternative genes of the WNT/APC/β-catenin and KRAS/BRAF/MEK pathways." (PMID 39452477, 2024). "According to recent evidence, the prognostic value of Vitamin D (VitD) status for colorectal cancer (CRC) patients might be confined to patients with the GG genotype of Cdx2, a functional polymorphism of the VitD receptor gene." (PMID 37375621, 2023). "The deficiency of CDX2 increases colorectal cancer susceptibility." (PMID 35449124, 2022). "To further explore this, we modeled Cdx2 loss in SW480 colorectal cancer cells." (PMID 33525395, 2021). "In conclusion, our study confirms (but also significantly relativizes) the general prognostic relevance of CDX2 loss in colorectal cancer (in univariate analyses) and shows its association with tumour localisation, microsatellite status and certain CRC subtypes." (PMID 34616012, 2021). "Next, we developed a model of colorectal cancer in the colon of Cdx2-Ano1fl/fl mice to determine whether the mutant mice had a greater susceptibility to colorectal cancer." (PMID 31383845, 2019). "Landau and coworkers provided evidence that CDX2 loss was observed not only in MSI-H BRAF-mutated colorectal cancers, but also in a subgroup of MSS BRAF-mutated colorectal cancers, characterized by an aggressive clinical phenotype and increased Cytokeratin 7 expression expression." (PMID 29652830, 2018). "Thus, Kim and coworkers have explored a large group of MSI-H colorectal cancers for CDX2 protein levels and observed that about 14% of these tumors exhibited CDX2 loss of expression." (PMID 29652830, 2018).
colorectal cancer (continued). "Recent studies suggest that the loss of expression of the homeobox protein CDX2 could represent an important molecular abnormality observed in colorectal cancer of the serrated type." (PMID 29652830, 2018). "Several retrospective studies suggested that the loss of CDX2 expression in colorectal cancers (CRCs) was associated with worse prognosis as well as several adverse prognostic variables, such as high histologic grade, BRAF mutations, and CpG island methylator phenotype positivity." (PMID 29682204, 2018). "The role of CDX2 as a tumor suppressor is also supported by the observation that its expression is decreased in human colorectal cancer, and reduced expression of CDX2 is associated with poor overall survival rates in patients with colorectal cancer." (PMID 26005051, 2015). "Our hypothesis is that Cdx2 loss may be an important marker of other molecular changes associated with the serrated pathway to colorectal cancer, including BRAF mutation and high-level CIMP." (PMID 24130965, 2013). "Interestingly, some studies have observed that MMR-deficient colorectal cancers show a frequent loss of Cdx2, a tumor suppressor gene and homeodomain transcription factor that functions to regulate intestinal epithelial cell differentiation." (PMID 24130965, 2013). "Furthermore, mutations in the CDX2 gene are highly uncommon in CRC—only 3 of 224 previously sequenced colorectal cancer cell lines and tumors harbor a mutation (0.9% mutant allele frequency), and all of those mutations occur in repeat sites of cancers with microsatellite instability." (PMID 39328205, 2024). "Immunohistochemical loss of CDX2 has been proposed as a biomarker of dismal survival in colorectal carcinoma (CRC), especially in UICC Stage II/III." (PMID 34616012, 2021). "As miR-196b was found to be directly activated by the CDX2 intestinal-specific transcription factor, implicated in colon cancer pathogenesis, we sought to determine whether miR-196b expression was misregulated in colorectal cancer (CRC)." (PMID 27902469, 2017). "CDX2, another HD protein, binds Ku70 through its HD domain in colorectal cancer cells but inhibits DNA–PK activity." (PMID 40114375, 2025). "CDX2 immunohistochemistry is inexpensive, widely available, and can stratify colorectal cancer patients into prognostic subgroups." (PMID 41388313, 2025). "CDX2, essential for intestinal epithelial differentiation, is downregulated in colorectal cancer, impairing normal differentiation processes and aiding tumor progression." (PMID 41411347, 2025). "Medullary carcinoma is often CDX2/CK20-negative in colorectal cancer, including typical poorly differentiated adenocarcinomas." (PMID 41030825, 2025). "In colorectal cancer (CRC), reduced expression levels of CDX2 and SATB2 have been associated with poor differentiation and worse survival." (PMID 39998677, 2025). "This immunoprofile differs from that of primary colorectal cancer, which generally shows strong CDX2 and SATB2 positivity." (PMID 41159019, 2025). "CDX2 promoter methylation was detected in 71.67% (43/60) of colorectal cancer cases, and 55.45% (61/110) of lung cancer cases." (PMID 40002854, 2025). "Among these genes, we observe only CDX2 to be a colorectal carcinoma–specific essential gene by DepMap." (PMID 41051921, 2025). "These seven cell lines had significantly higher expression of CDX2 than the other 46 colorectal carcinoma (Wilcoxon rank-sum test P = 0.01), with four of seven also having chr 13q gain (the remaining three samples did not have CN status data)." (PMID 41051921, 2025). "Although on average the dependency scores for CDX2 were lower than other cancer types, only 13% (7/53) of the colorectal carcinoma cell lines had a relevant dependency score for CDX2." (PMID 41051921, 2025).
colorectal cancer (continued). "Subsequently, we adoptively transferred bone marrow cells from Il17ra ΔTreg mice to a mouse model of sporadic colorectal cancer (Cdx2-Cre +/Apc F/+), to selectively ablate IL-17 direct signaling on Tregs in colorectal cancer." (PMID 38947320, 2024). "These factors collectively underscore the need for further research to refine the assessment methods of CDX2 and expand the scope of investigation to enhance the prognostic utility of CDX2 in colorectal cancer management." (PMID 38786321, 2024). "While confirming the prognostic utility of CDX2 in colorectal cancer, our study highlights that larger studies are required to confirm its utility as a predictive chemotherapy biomarker, especially in left-sided and rectal cancers." (PMID 39201360, 2024). "The rate of MS4A12 positivity in colorectal cancer is as high as 63%, and MS4A12 expression is regulated by the transcription factor caudal type homeobox 2 (CDX2), which can influence the proliferation and cell cycle of colorectal cancer cells." (PMID 39717774, 2024). "Tumour tissue samples from 668 patients with stage I–IV colorectal cancer were stained for CDX2 and stratified into two subgroups according to expression levels." (PMID 39201360, 2024). "In the current investigation, the group of colorectal cancers with CDX2 suppression was confirmed to contain a high percentage of MSI-high tumors and tumors with a TMB above 10 mutations/Mb." (PMID 39452477, 2024). "Some studies also suggest that CDX2 expression is higher in left-sided than right-sided colorectal cancer, which is concordant with our results showing that high CDX2 expression was higher in the left-sided (94%) than right-sided samples (88%)." (PMID 39201360, 2024). "Existing CDX2 cut-off immunohistochemical scoring models, as discussed in Section 4.2 (Evaluation of CDX2 Expression in Colorectal Cancer), tend to oversimplify by uniformly classifying tumors as CDX2-positive, -moderate, or -negative." (PMID 38786321, 2024). "CDX2 is commonly expressed in colorectal cancers, making it a valuable marker for understanding the disease." (PMID 38786321, 2024). "The majority of CDX2-suppressed colorectal cancers (54.1%) were MSI high, while only a few cases of non-CDX2-suppressed cancers were MSI high." (PMID 39452477, 2024). "In contrast to the two RAS genes, mutations in other genes of the RAS/RAF/MEK pathway were more prevalent in CDX2-suppressed colorectal cancers." (PMID 39452477, 2024). "Mutations in other components of the pathway, including PTEN, TSC1, PPP2R1A, and MTOR, were also significantly more frequent in CDX2-suppressed colorectal cancers." (PMID 39452477, 2024). "These landscapes suggest that CDX2-suppressed and non-CDX2-suppressed colorectal cancers use different molecular alterations to activate the same cancer-associated pathways." (PMID 39452477, 2024). "Among the regulons driving classical states were those driven by TBX10, PDX1, FOXA3 and CDX2, which is a known prognostic marker in gastrointestinal cancers, especially colorectal cancer, and has been described as a lineage survival oncogene." (PMID 39417106, 2024). "The most sensitive markers for GI origin were GPA33 (positive in 98%, 60%, and 100% of pulmonary metastases from colorectal cancer, pancreatic cancer, and other GI adenocarcinomas, respectively), CDX2 (99/40/100%), and CDH17 (99/0/100%)." (PMID 37349623, 2024). "In conclusion, the group of colorectal cancers with CDX2 mRNA suppression represents a sub-set of the disease with a landscape offering opportunities for therapeutic targeting." (PMID 39452477, 2024). "Our data further support that CDH17, GPA33, and SATB2 in addition to CDX2 are all very sensitive markers for colorectal cancer metastases, and slightly more sensitive than CK20." (PMID 37349623, 2024). "Immunohistochemistry showed a focally positive CDX2, which is a sensitive marker for colorectal carcinoma and commonly expressed in DA." (PMID 39376805, 2024).